HHLA2 (HHLA2 member of B7 family)
Diseases named in the same sentence as HHLA2 in open-access papers (continued):
Sharing a sentence is not in itself a finding about the gene and the disease.
hepatocellular carcinoma (10 papers, 2022 to 2025). A malignant tumor that arises from hepatocytes. "RandomForest analyses (371 cases), qRT-PCR (15 cases), and immunohistochemical staining (189 cases) were used to validate the prognostic value of HHLA2 in hepatocellular carcinoma (HCC) patients." (PMID 35371079, 2022). "HHLA2 has been reported to be positively correlated with immune infiltration in liver cancer, and its upregulation induces M2 polarization and chemotaxis, contributing to immune escape and the development of hepatocellular carcinoma." (PMID 38951802, 2024). "HHLA2 was also overexpressed in hepatocellular carcinoma (HCC) compared with para-carcinoma regions and healthy tissues; moreover, HHLA2 mRNA was expressed prominently in tumor tissue compared with adjacent tissue in 67 HCC cases." (PMID 38786018, 2024). "HHLA2 binds to its ligand TMGD2 (CD28H) in HCC to activate the JAT/STAT signaling pathway, leading to the dysfunction of T cells and promoting the immune tolerance of hepatoma cells." (PMID 36992198, 2023).
intrahepatic cholangiocarcinoma (9 papers, 2019 to 2025). A carcinoma that arises from the intrahepatic bile duct epithelium in any site of the intrahepatic biliary tree. "Multiple studies have demonstrated that HHLA2 expression is significantly associated with a poor prognosis in patients with intrahepatic cholangiocarcinoma." (PMID 40909948, 2025). "Experiments have proved that HHLA2 has prognostic significance and is more widely expressed as an immune checkpoint compared with PD-L1 in intrahepatic cholangiocarcinoma 33, which prove the feasibility of HHLA2 as a new immune checkpoint in liver tumors." (PMID 34093808, 2021).
liver cancer (9 papers, 2019 to 2025). An epithelial or non-epithelial malignant neoplasm that arises from the liver. "This phenomenon is attributed to the expression of HHLA2 in liver cancer cells, which induces M2 polarization and the chemotactic migration of macrophages." (PMID 40909948, 2025). "A recent investigation into liver cancer has elucidated the role of IRF-1 in regulating the downstream factor HHLA2, facilitating immune escape, and promoting tumor progression." (PMID 40909948, 2025). "We revealed that high HHLA2 expression indicated worse outcome in early-stage of Barcelona Clinic Liver Cancer staging system (BCLC) (overall survival: P=0.0010; TTR: P=0.0044)." (PMID 35371079, 2022). "Additionally, the regulation of HHLA2 expression by the IFN-γ/STAT1 pathway has only been observed in liver cancer; further investigation is required to explore the potential therapeutic effects of targeting this pathway to regulate HHLA2 expression in other gastrointestinal tumors." (PMID 40909948, 2025). "However, HHLA2’s biological functions in liver cancer are yet to be closely examined." (PMID 35371079, 2022). "The high expression rates of HHLA2 in the two independent ICC cohorts were 49.0 and 67.7% respectively, which was on a medium to high end of the expression spectrum, higher than previous data on gall bladder cancers (0/10) and liver cancers (4/10)." (PMID 30885276, 2019). "Interestingly, methyltransferase genes were downregulated in tumors and the adjacent tissue regardless of the HHLA2 expression level, suggesting that methylation may be the factor influencing HHLA2 expression in liver cancer." (PMID 38786018, 2024).
melanoma (8 papers, 2018 to 2025). A malignant, usually aggressive tumor composed of atypical, neoplastic melanocytes. "For example, the ERV-derived immune checkpoint HHLA-2 is expressed in many types of human cancers such as melanoma, breast, colon, pancreatic, among others, and high HHLA-2 expression is associated with poor prognosis." (PMID 40387511, 2025). "In summary, our findings presented an association between HHLA2 expression and the response to immunotherapy in melanoma." (PMID 36003385, 2022). "This study focuses on illustrating the prognostic value of HHLA2 in melanoma immunotherapy and its association with tumor-infiltrating lymphocytes." (PMID 36003385, 2022). "In general, high HHLA2 expression was associated with an immune-activated microenvironment characterized by increased infiltration of CD8+ T cells in melanoma." (PMID 36003385, 2022). "In our study, high HHLA2 expression represented an improved response of immunotherapy, and was significantly and consistently associated with a better PFS and OS of melanoma immunotherapy." (PMID 36003385, 2022). "Colocalization experiments by immunofluorescence showed that HHLA2 mainly expressed in melanoma cells, but minorly expressed in CD45+ immune cells." (PMID 36003385, 2022). "Firstly, the cohort was from a single institution in China, and the expression pattern of HHLA2 in melanoma patients from other institutions is required to be studied." (PMID 36003385, 2022). "Through GO analysis and KEGG analysis, we found that HHLA2 played an important role in the immune regulation of melanoma." (PMID 36003385, 2022). "Our finding further confirmed that HHLA2 served as an important co-stimulative molecule in melanoma, and was necessary for the activation of tumor immune microenvironment." (PMID 36003385, 2022). "Our study for the first time revealed the potential predictive function of HHLA2 expression pattern on the prognosis of melanoma patients who accept immunotherapy." (PMID 36003385, 2022). "In this study, we mainly aimed to figure out the relationship between HHLA2 expression and clinicopathological characteristics, prognosis and immune infiltrations of melanoma." (PMID 36003385, 2022). "All these findings suggested that HHLA2 played a positive role in the immune microenvironment of melanoma, which explained for our results." (PMID 36003385, 2022). "HHLA2, a new-found member of B7 family, is generally expressed in kinds of tumors, such as melanoma." (PMID 36003385, 2022). "By far as we acknowledge, there has not any study focusing on clarifying the relationship between the expression of HHLA2 and the prognosis of melanoma patients treated by immunotherapy that has been reported to date." (PMID 36003385, 2022). "Meanwhile, the relationship between HHLA2 and tumor immune microenvironment of melanoma has yet been explored." (PMID 36003385, 2022). "In conclusion, we applied immunohistochemistry to analyze HHLA2 expression pattern in melanoma, and evaluated the influence of HHLA2 expression levels on the efficacy of immunotherapy in ICB-treated patients with advanced or unresectable melanoma." (PMID 36003385, 2022). "Tumor tissues from 81 cases with advanced and unresectable melanoma were collected for detecting HHLA2 and CD8 levels by immunohistochemistry." (PMID 36003385, 2022). "Melanoma with high expression of HHLA2 predicts a better prognosis." (PMID 38835341, 2024). "In general, HHLA2 has the same predictive effect in different types of melanoma in our cohort." (PMID 36003385, 2022). "Moreover, immunohistochemistry (IHC) analyses of FFPE tissue from melanoma patients revealed that HHLA2 high expression was strongly related to improved response to ICB and indicated a longer progression-free survival (PFS) and overall survival (OS)." (PMID 36003385, 2022).
melanoma (continued). "As a result, analyses revealed that increased HHLA2 expression was associated with better ICB response and increased infiltration of CD8+ T cells in the cohort study of Asian patients diagnosed with advanced or unresectable melanoma." (PMID 36003385, 2022). "It has been demonstrated that HHLA2 protein could be widely found in many human cancer tissues, such as breast, lung, thyroid, melanoma, pancreas, ovary, liver, bladder, colon, prostate, kidney, and esophagus cancers." (PMID 31015801, 2019). "Therefore, HHLA2 may work as an essential co-stimulative molecule in melanoma immune microenvironment." (PMID 36003385, 2022). "Therefore, it is necessary to use another melanoma cohort to re-confirm the relationship between HHLA2 and CD8 positive T cell infiltration and other related immune cell infiltration, which can also help to understand the role of HHLA2 as a co-stimulative molecule in melanoma." (PMID 36003385, 2022). "They found a positive correlation between HHLA2 and CD8+ levels in tissues from 81 patients with advanced unresectable melanoma." (PMID 38835341, 2024). "Although the expression of HHLA2 in melanoma is not as high as other tumors, it is high enough to be distinguished from normal tissues." (PMID 36003385, 2022). "Furthermore, the overall response rate (ORR) was 50% in HHLA2-positive patients and 14.3% in negative patients, suggesting that high HHLA2 expression could be recognized as a sign of better response to immunotherapy in melanoma patients." (PMID 36003385, 2022).
ovarian carcinoma (7 papers, 2021 to 2025). A malignant neoplasm originating from the surface ovarian epithelium. "On the other hand, higher HHLA2 expression was associated with a higher differentiation of ovarian cancer, but only 64 OC samples were included in this study." (PMID 38786018, 2024). "Only 17.2% of ovarian cancer patients showed HHLA2 expression, which was significantly associated with the differentiation of ovarian cancer cells (p = 0.027), and well-differentiated tumours expressed higher levels of HHLA2." (PMID 33962626, 2021). "An association was found between HHLA2 expression and the degree of differentiation of ovarian cancer (p = 0.027)." (PMID 33962626, 2021). "We found that HHLA2 was highly expressed in normal ovarian epithelium with a positive rate of 43.75% (7/16), which was significantly higher than that in ovarian cancer tissues (p = 0.041), indicating the association of reduced HHLA2 expression with pathological changes during tumourigenesis." (PMID 33962626, 2021). "Along with previously reported findings that HHLA2 behaves as a co-stimulatory ligand, our study suggests that the loss of HHLA2 may contribute to the immunosuppressive microenvironment and progression of ovarian cancer." (PMID 33962626, 2021). "Ovarian cancer cells may escape activated T-cell attack through the loss of HHLA2 protein expression." (PMID 33962626, 2021). "The issue is more complicated in the cases of gastric, pancreatic, and ovarian cancer, where studies present contradictory results regarding HHLA2 expression." (PMID 38786018, 2024). "By contrast, in epithelial ovarian cancer, HHLA2 expression is found to significantly correlated with cancer cell differentiation in which higher HHLA2 level was identified in well-differentiated cancers." (PMID 38144305, 2023). "HHLA2 is associated with tumour differentiation and high CD8+ TIL levels; and predicts improved survival in ovarian cancer." (PMID 33962626, 2021). "As a proof-of-concept, low HHLA2-expressing OVCAR-3 and PEO1 cells were selected to construct HHLA2-overexpressing cell lines to investigate the intrinsic biological function of HHLA2 in ovarian cancer." (PMID 33962626, 2021). "Future studies to determine the biological function of HHLA2 in ovarian cancer are warranted to further elucidate their contributions to tumour progression." (PMID 33962626, 2021). "Kaplan–Meier survival analysis of HHLA2 expression and other clinicopathologic characteristics in patients with ovarian cancer was performed." (PMID 33962626, 2021). "HHLA2 expression in ovarian cancer cell lines was initially measured, revealing that HHLA2 is highly expressed in A2780 and SK-OV-3 cells and weakly expressed in other cell lines." (PMID 33962626, 2021). "Our Study suggested that HHLA2 expression is higher in well-differentiated ovarian cancer than in poorly differentiated ones." (PMID 33962626, 2021). "We performed immunohistochemistry to examine HHLA2 expression in 64 ovarian cancer tissues and 16 normal ovarian tissues." (PMID 33962626, 2021). "The MTT and EdU assays both revealed that HHLA2 overexpression significantly reduced the proliferation of ovarian cancer cells." (PMID 33962626, 2021). "For the first time, HHLA2 expression in epithelial ovarian cancer tissue and its clinical significance were examined." (PMID 33962626, 2021). "The MTT assay and EdU proliferation assays were conducted to determine the function of HHLA2 in ovarian cancer cells." (PMID 33962626, 2021). "In poorly and moderately differentiated ovarian cancer, the proportions of HHLA2-positive patients were 7.69 and 16%, respectively; in well-differentiated patients, the proportion of HHLA2 positive patients was 38.46%." (PMID 33962626, 2021). "We found that HHLA2 positivity is less common in epithelial ovarian cancer than in normal ovarian and fallopian tube epithelium, and high HHLA2 expression is an indicator of lower malignant tumour behaviour and a better prognosis in ovarian cancer." (PMID 33962626, 2021).
ovarian carcinoma (continued). "In ovarian cancer, one study suggested that high HHLA2 expression in tumor cells could predict improved survival." (PMID 40255615, 2025). "The research to date presents contradictory conclusions regarding HHLA2’s role in ovarian cancer." (PMID 38786018, 2024). "Additionally, we also found that overexpressing HHLA2 inhibited the proliferation of ovarian cancer cells." (PMID 33962626, 2021). "Beyond that, we also elucidate the cell-intrinsic effects of HHLA2 in ovarian cancer cells." (PMID 33962626, 2021). "The HHLA2 expression profile in the Oncomine dataset also supports our result that the expression level in the normal ovary is significantly higher than that in ovarian cancer (p = 0.004)." (PMID 33962626, 2021). "HHLA2 was mainly expressed in the cytoplasm and membrane in ovarian cancer cells." (PMID 33962626, 2021). "Additionally, upregulated HHLA2 can inhibit the proliferation of ovarian cancer cells, supporting our findings that high HHLA2 expression is a favourable predictor for patient survival in ovarian cancer." (PMID 33962626, 2021). "In the present study, the intrinsic function of HHLA2 in ovarian cancer cells was explored." (PMID 33962626, 2021). "Our present study examined the expression of HHLA2 in ovarian cancer and analysed its relationship with clinicopathologic features and prognosis to further explore its role in ovarian cancer, providing a primary foundation for the discovery of new immunotherapeutic targets for ovarian cancer." (PMID 33962626, 2021). "Although the clinical significance of HHLA2 in some solid tumours has been clarified in recent years, the clinical significance and function of HHLA2 in ovarian cancer remains unclear." (PMID 33962626, 2021). "The level of HHLA2 protein in epithelial ovarian cancer tissue obtained from 64 patients with ovarian cancer who had undergo surgical resection between 2007 and 2011 was examined, and it was graded as follows: absent staining, weak staining, moderate staining, and strong staining." (PMID 33962626, 2021). "In this study, HHLA2 is more expressed in normal ovarian tissue than in cancerous tissue and high HHLA2 could serve as an independent prognostic factor for ovarian cancer, indicating that HHLA2 expression is negatively correlated with the tumorigenesis and progression of ovarian cancer." (PMID 33962626, 2021). "Furthermore, the biological function of HHLA2 in ovarian cancer cells was initially explored." (PMID 33962626, 2021). "Therefore, to elucidate the relationships between HHLA2 expression and PD-L1 and B7x expression in ovarian cancer, the CCLE database was used to analyse the mRNA levels of HHLA2, PD-L1, and B7x in 47 ovarian cancer cell lines using Spearman’s correlation analysis." (PMID 33962626, 2021). "Therefore, HHLA2 or its receptors may represent attractive targets for ovarian cancer patients." (PMID 33962626, 2021). "Therefore, HHLA2 may influence T cell infiltration as a co-stimulatory molecule in ovarian cancer." (PMID 33962626, 2021). "The correlation between HHLA2 expression and CD8+ T cells in ovarian cancer was evaluated in the present study." (PMID 33962626, 2021). "The role of HHLA2 in ovarian cancer (OC) is not clear, and the number of studies on the topic is limited." (PMID 38786018, 2024). "HHLA2 may stimulate T effector cells (CD8+ T cells) through different receptors in ovarian cancer, leading to the killing effect of CD8+ T cells in ovarian cancer." (PMID 33962626, 2021). "Tumour-infiltrating CD8+ T cells were more numerous in HHLA2-positive ovarian cancer than in HHLA2-negative ovarian cancer." (PMID 33962626, 2021). "HHLA2 expression was not correlated significantly with PD-L1 nor B7x expression in ovarian cancer." (PMID 38786018, 2024).
ovarian carcinoma (continued). "Our findings offer an alternative hypothesis: HHLA2 may act as a co-stimulatory ligand in ovarian cancer, and the absence of HHLA2 expression may contribute to the establishment of an immunosuppressive tumour microenvironment and tumour progression." (PMID 33962626, 2021). "In our study, the MTT assay and EdU staining assay showed that HHLA2-overexpressing ovarian cancer cells exhibited decreased proliferation ability compared with the normal groups, indicating that HHLA2 can inhibit the proliferation of ovarian cancer cells independent of an immune environment." (PMID 33962626, 2021). "However, HHLA2 was not expressed in most ovarian cancer tissues, and its expression was only observed in a few ovarian cancer tissues." (PMID 33962626, 2021). "In addition, we also find that HHLA2 inhibited ovarian cancer cells proliferation without the affecting immune cells in vitro." (PMID 33962626, 2021). "Therefore, we speculate that HHLA2 was unlikely to be co-expressed with PD-L1 or B7x in ovarian cancer." (PMID 33962626, 2021). "Thus, the receptors that can interact with HHLA2 expressed in ovarian cancer cells may not be TMIGD2." (PMID 33962626, 2021). "Comparison of the CD8+ T-cell infiltration between HHLA2-positive and -negative patients illustrated that the CD8+ T-cell density was increased in patients with HHLA2-positive ovarian cancer." (PMID 33962626, 2021).
renal cell carcinoma (7 papers, 2020 to 2024). "Although the correlations between HHLA2 expression and prognosis in renal cell carcinoma are unclear, several authors included it in highly reliable prognostic models for RCC." (PMID 38786018, 2024). "METTL3, acting as a “writer,” was found to be a methylation regulator inhibiting the expression of HHLA2 in renal cell carcinoma." (PMID 36765416, 2023). "However, it could also promote the tumorigenesis of human renal cell carcinoma by mediating HHLA2 mRNA m6A modification." (PMID 39103890, 2024). "Therapeutics targeting HHLA2 or its inhibitory receptor KIR3DL3 are being developed for solid tumors, including renal cell carcinoma (RCC)." (PMID 37891555, 2023).